MTOR (mechanistic target of rapamycin kinase)
Diseases named in the same sentence as MTOR in open-access papers (continued):
Sharing a sentence is not in itself a finding about the gene and the disease.
metastatic disease (continued). "Current systemic therapeutic approaches include inhibiting pathways of angiogenesis, immune checkpoint blockade, and mTOR inhibition, but inevitably resistance develops for those with metastatic disease, and novel treatment strategies are urgently needed." (PMID 32872127, 2020). "RAPA is a potent, naturally occurring mTOR inhibitor, which prevents primary and metastatic tumor growth by antiangiogenesis." (PMID 32013948, 2020). "Medical treatments that can be considered for unresectable/metastatic disease, include those that are implemented in sporadic th-NETs such as SSAs, chemotherapy, mTOR inhibitors, and PRRT." (PMID 31263451, 2019). "Alternative mTOR signaling appears to be upregulated in human patients with cancer, specifically in patients with metastatic disease." (PMID 31288154, 2019). "The median survival of patients with metastatic disease is about 4 months while it increases with the use of TKIs and mTOR inhibitors, and the survival depends on the grade of the tumour and prognostic grading criteria that are proposed." (PMID 29409504, 2018). "For advanced metastatic disease, systemic treatment, including inhibition of vascular endothelial growth factor pathways and mTOR pathways, as well as immunotherapy are available." (PMID 29479523, 2018). "Alterations in expression of components of the PI3K/Akt/mTOR occur in 42% of primary prostate tumors and 100% of metastatic tumors." (PMID 30453546, 2018). "A p-mTOR QS higher than 4.5–4.9 correlated with metastatic disease at diagnosis (AUC 0.783 ± 0.057; p < 0.001)." (PMID 29213282, 2017). "Receiver-operating-characteristic curves were used to determine the best cut-off ranges above which p-mTOR QS correlated with metastatic disease at diagnosis." (PMID 29213282, 2017). "Based on these data, mTOR inhibition was evaluated as an adjuvant treatment for recurrent/metastatic disease." (PMID 27015118, 2016). "Although several targeted therapeutics such as vascular endothelial growth factor (VEGF) and mammalian target of rapamycin (mTOR) inhibitors have been approved for the treatment of metastatic disease over the past 10 years, metastatic RCC is still incurable." (PMID 26426994, 2015). "At the time of referral to the CCTT the patient had metastatic disease to her lungs, mediastinal and hilar nodes, porta hepatis, peritoneum, and liver and subsequently received experimental therapy with mTOR inhibitor sirolimus (4 mg orally daily)." (PMID 24931142, 2014). "In our case, metastatic tumors changed the vascularity quickly after TKI or mTOR inhibitor administration and got the resistance against administered one and had sensitivity to another one." (PMID 22970402, 2012). "Poorer OS was seen in patients who developed metastatic disease especially in the brain and liver, and with p110α and mTOR overexpressing tumours." (PMID 22454081, 2012). "This approach is as yet unproven in the adjuvant setting or following resection of metastatic disease, but mTOR inhibition is emerging as an attractive treatment option as more information on its use in LAM and AML returns." (PMID 22619565, 2012). "Given the lack of benefit of traditional cytotoxic therapy in the metastatic setting, mTOR inhibition in the setting of a clinical trial should be strongly considered in any patient with recurrent or metastatic disease." (PMID 22619565, 2012). "In our study, we determined that mTOR expression increased even more in metastatic tumors." (PMID 40566531, 2025). "Patients with metastatic disease may be treated with chemotherapy (preferably temozolomide-based), somatostatin analogues, mTOR inhibitors, or PRRT with 177Lu-DOTATATE." (PMID 38001701, 2023). "However, the mTOR inhibitor everolimus seemed to have a significant palliative progression-slowing effect in one patient with extensive metastatic disease." (PMID 35696052, 2022).
metastatic disease (continued). "Rapamycin is a classic inhibitor of mTOR, and previous research has shown that this inhibitor inhibits growth and angiogenesis in metastatic tumors by reducing VEGF production and blocking VEGF-induced endothelial cell signaling in a CT-26 cell-transplanted tumor model." (PMID 33644083, 2020). "Although molecular targeted therapies (MTTs), such as mammalian target of rapamycin (mTOR) inhibitors and tyrosine kinase inhibitors, have been shown to improve outcomes in patients with metastatic disease, resistance to molecular targeted therapies often occurs." (PMID 32114655, 2020). "Though warranted in HNSCC in general, careful patient selection or retrospective analysis may be necessary, as HPV+, mTOR activated, or therapy resistant recurrent/metastatic disease may be of greatest benefit." (PMID 27015118, 2016). "Furthermore, establishing a cohort of samples from patients with known recurrent and metastatic disease to survey mTOR activation would help to identify a population of potential benefit." (PMID 27015118, 2016). "However, we have found in the present study that different selective Mediator kinase inhibitors suppress the growth of TNBC tumors, extend the survival of metastatic disease, and potentiate drugs targeting mTOR and AKT, preventing, at least in some cases, the tumor adaptation to therapy." (PMID 39541354, 2024). "For metastatic disease state, treatment options include systemic therapy with multitarget tyrosine kinase inhibitors (TKIs), including sunitinib, cabozantinib, and pazopanib as well as mammalian target of rapamycin (mTOR) inhibitors such as everolimus or temsirolimus, offering only modest benefits." (PMID 32106629, 2020). "Further, activation of the AKT/mTOR pathway is observed in metastatic tumors, and increased phosphorylation of AKT, mTOR, and HER2 correlate with poor outcome for disease-free survival." (PMID 39000231, 2024). "Loss of Stat3 in a Pten-null mouse prostate model leads to a reduction of LKB1/pAMPK with simultaneous activation of mTOR/CREB, resulting in metastatic disease." (PMID 37573301, 2023). "Existing studies have confirmed that PLC-β, mammalian target of rapamycin (mTOR) and MAPK-related signaling pathways are potential therapeutic targets for metastatic tumors." (PMID 37576896, 2023). "Although, there are more than half a dozen novel targeted agents currently in use for metastatic disease, these therapeutics aim at only two pathways: vascular endothelial growth factor (VEGF) signaling and the mammalian target of rapamycin (mTOR)." (PMID 29108248, 2017). "In the setting of residual metastatic disease, following nephrectomy, or recurrent metastatic disease, the Task Force discussed the role of first-line treatment with immunotherapy versus VEGF or mTOR targeted therapy for metastatic disease." (PMID 27891227, 2016). "There were seven patients in the study who received small-molecule inhibitors (SMIs), such as tyrosine kinase inhibitors (TKIs), mammalian target of rapamycin (mTOR) inhibitors, and isocitrate dehydrogenase (IDH) inhibitors, for the treatment of metastatic disease." (PMID 37174084, 2023). "Collectively, our analysis of single cell sequencing data suggested that the TME of primary tumor of NSCLC are enormously immunosuppressive than the metastatic tumor and are populated by high expression levels of EGFR/MAP2K1/MTOR/TEAD1/YAP1 within tumor microenvironment of NSCLC." (PMID 35655775, 2022). "In our study, mTOR was under expressed in 88% of patients, but it was increased in patients with adverse prognostic factors such as micro vascular invasion and metastatic disease, although not statistically significant." (PMID 29202733, 2017). "The exception was metastatic tumor xenograft SUTI151M, although both treatments still inhibited its growth by over 90%, raising the possibility of other potential modes of action of mTOR inhibitors." (PMID 24708766, 2014).
metastatic disease (continued). "For the approximately one-third of patients who present with metastatic disease, there are several FDA-approved drugs available, among them the multi-kinase inhibitors (e.g. sorafenib and sunitinib) and the mammalian target of rapamycin (mTOR) inhibitors." (PMID 23951092, 2013). "The addition of an already FDA approved and well-tolerated mTOR inhibitor, such as rapamycin, to standard-of-care CRT may also provide a treatment option for patients with recurrent/metastatic disease, for which effective treatment options are currently lacking." (PMID 27015118, 2016). "Systems biology bioinformatics approaches will be needed to determine whether or not multiple aberrant signals in patients with metastatic tumors converge on pathways such as PI3K/AKT/mTOR pathway, and are hence actionable." (PMID 24912489, 2014). "Thus, the management of metastatic disease highly depends on targeted therapies, such as anti-vascular endothelial growth factor (VEGF) antibodies, VEGF receptor tyrosine kinase inhibitors, mammalian target of rapamycin (mTOR) pathways inhibitors and immune checkpoint inhibitors." (PMID 38136171, 2023). "No standard systemic treatment option is available for metastatic disease, though most medical oncologists prescribe vascular endothelial growth factor receptor tyrosine kinase inhibitors (VEGFR TKIs) or mammalian target of rapamycin (mTOR) inhibitors." (PMID 31182090, 2019).
meningioma (65 papers, 2013 to 2026). A generally slow growing tumor attached to the dura mater. "The AKT1 variant AKT1E17K found in meningiomas activates the mTOR signaling pathway, which promotes cell growth, survival, and proliferation while inhibiting apoptosis." (PMID 41372821, 2025). "It is a suggested oncogenic driver and is frequently associated with PI3K/AKT/mTOR pathway in driving tumor formation in meningiomas." (PMID 37898750, 2023). "FAK and mTOR inhibitors are a promising advancement in targeted meningioma therapy, in individuals with NF2 associated or NF2 related meningioma." (PMID 37860270, 2023). "Among the cohort, high p-mTOR expression was significantly associated with recurrence in atypical meningioma." (PMID 35216092, 2022). "Disruptions in the mTOR pathway are well documented in high grade meningiomas, with mTOR inhibition associated with decreased proliferation in vitro." (PMID 35402234, 2022). "mTOR pathways, which are activated by meningiomas with ATK1 and PIK3CA mutations, are also being targeted by mTOR inhibitors everolimus and vistusertib (NCT03071874, NCT01880749)." (PMID 34638590, 2021). "High-grade meningiomas are nearly exclusively associated with NF-2 mutations or q22 deletions, with only 5% of high-grade meningiomas harboring mutations in mTOR, Sonic hedgehog or other known tumorigenic pathways." (PMID 34638590, 2021). "In meningioma cell lines and patient samples deficient in Merlin, constitutive activation of mTOR signaling and overexpression of mTORC1 has been observed." (PMID 31970090, 2019). "A total of 23 case-control studies matched the inclusion criteria, including one that discussed the relationship between mTOR polymorphisms and meningioma, which is generally considered to be benign." (PMID 27462867, 2016). "Recent studies have found the mammalian target of rapamycin (mTOR) to be also involved in the signaling pathways associated with meningioma tumorigenesis." (PMID 25965831, 2015). "Similarly, considerable activation of mutated AKTs in the PI3K/AKT/mTOR pathway is also reported in some meningiomas, and trials of inhibitors of these pathways (capivasertib, alpesilib, vistusertib) are also ongoing." (PMID 36672431, 2023). "Recent in vitro data has also suggested that skull-based meningiomas with KLF K409Q mutations have a unique tumor phenotype that may respond to mammalian target of rapamycin (mTOR) inhibition with temsirolimus." (PMID 36686824, 2022). "A preclinical study found that 9% of 108 meningiomas demonstrated mutations in the PI3K/AKT/mTOR pathway, suggesting it may play an important role in the growth of meningiomas." (PMID 36033542, 2022). "OGN has been implicated in meningioma through effects on mTOR and NF2 signaling, but whether it may be a therapeutic target is unclear." (PMID 33622177, 2021). "As such, drugs targeting the mTOR hold promise for treatment of NF2-mutated meningiomas." (PMID 31970090, 2019). "In addition, NF2 alterations combined with abnormalities in AKT1 and mTOR are associated with the overgrowth of various tissues, which could be responsible for the recurrence of meningiomas." (PMID 35712491, 2022). "The brigatinib + INK128 combination exhibits antitumor synergy in both the AG-NF2-Men and Ben-Men-1 meningioma models, suggesting combining brigatinib with mTOR inhibition to more effectively treat NF2-SWN and sporadic NF2-deficient meningiomas." (PMID 41417846, 2026). "Everolimus, an mTOR inhibitor, slows tumor cell growth and is being investigated for patients with resistant meningiomas." (PMID 40787520, 2025). "The combination of the mTOR inhibitor everolimus and the somatostatin agonist octreotide has shown promise in treating aggressive meningioma." (PMID 40787520, 2025). "Inhibitors of the mTOR pathway, such as temsirolimus and everolimus, have demonstrated efficacy in inhibiting meningioma growth." (PMID 40113789, 2025).
meningioma (continued). "In meningiomas, aberrant activation of EphA2 and EphB1 promotes proliferation through engagement with mTOR and ERBB3 signaling pathways." (PMID 41200151, 2025). "Building on the exploration of anti-angiogenic therapies, mTOR inhibitors have also gained attention as a potential therapeutic approach for managing recurrent meningiomas." (PMID 40787520, 2025). "In a study by Graillon el al.comparingthe effects of pasireotide to those of octreotide in vitro on meningioma primary cell cultures, combining an SST analog with an mTOR inhibitor like everolimus has demonstrated efficacy in treating aggressive meningiomas." (PMID 38919490, 2024). "The mTOR protein complex, a part of the PI3K complex, is crucial for meningioma development, and the mTOR inhibitor everolimus has demonstrated an increase in PFS and a decrease in tumor growth rate." (PMID 39202270, 2024). "The results show that the expression of β‐TrCP decreases in NF2‐associated meningioma cells after treatment with rapamycin (2 μmol/L 48 h), suggesting that the stability of PDL1 can also be regulated by inhibiting the mTOR pathway." (PMID 38828669, 2024). "Anti-VEGF molecules and mTOR inhibitors have shown potential in the treatment of high-grade and recurrent meningiomas where surgical and/or radiotherapy have been less effective." (PMID 39202270, 2024). "In particular, the role of merlin, whose function is related to the control of the mammalian target of the rapamycin (mTOR) pathway, has been considered, and in mouse models specific mTOR inhibitors (temsirolimus and everolimus) suppress meningioma growth." (PMID 38137885, 2023). "In human schwannomas and meningiomas, loss of NF2 leads to activation of PI3K/AKT/mTOR and thereby inhibits cancer cell proliferation." (PMID 37351538, 2023). "Of note, KLF4-mutated meningiomas exhibit higher sensitivity to mTOR inhibitors such as temsirolimus, underlining the potential role of the PI3K/AKT/mTOR pathway as potential treatment target in meningioma." (PMID 36181606, 2023). "For example, the peptide octreotide, a somatostatin agonist, has been used in combination with an mTOR inhibitor for aggressive and recurrent meningiomas where they have shown to be effective and well tolerated." (PMID 37835469, 2023). "Inhibitors of mTOR such as vistusertib are currently under investigation and early results in aggressive subsets of meningioma show promise." (PMID 37860270, 2023). "High levels of active phosphorylated mTOR were associated with shorter PFS and increased recurrence in atypical meningiomas." (PMID 38001599, 2023). "A recent clinical trial (CEVOREM) tested a combination of mTOR inhibitor everolimus and the somatostatin agonist octreotide on aggressive meningiomas." (PMID 37760490, 2023). "Consistently, AKT1E17K was associated with reduced time to meningioma recurrence and PI3K/AKT/mTOR oncogenic pathway, which is the most frequently mutated pathway in human cancer." (PMID 36937440, 2023). "The mTOR protein complex is an integral part of the PI3K complex, a pathway linked to the development of meningiomas." (PMID 37760490, 2023). "In contrast, inhibitors targeting the Pi3K-AKT-mTOR pathway upstream of mTOR remain poorly studied in meningioma." (PMID 36139608, 2022). "Studies have indicated that the overactivation of mTOR results in a high mitotic index and contributes to the recurrence of meningioma and poorer outcomes." (PMID 35712491, 2022). "The AKT/mTOR pathway was shown to be activated in meningioma, and mTOR inhibitors suppressed meningioma cell growth in vitro and in vivo." (PMID 35406478, 2022). "According to ClinicalTrials.gov, there are two ongoing clinical trials examining the effects of mTOR inhibitors in meningioma patients." (PMID 35216092, 2022). "In particular, it highlights the relationship between mTOR and merlin and elucidates the potential role of autophagy and redox reactions in the development of meningioma tumors." (PMID 35216092, 2022).